SMAGP (small cell adhesion glycoprotein)
Description:
May play a role in epithelial cell-cell contacts. May play a role in tumor invasiveness and metastasis formation.
Synonyms: MGC149453; MGC149454; hSMAGP
Tractability: Antibody: UniProt places it where antibodies can reach, with high confidence; its Gene Ontology location is reachable by antibodies, with high confidence; UniProt predicts a signal peptide or a membrane-spanning region; the Human Protein Atlas places it where antibodies can reach. PROTAC: ubiquitination databases record sites on it; its protein half-life has been measured.
Gene: Protein-coding gene on chromosome 12 (51,244,558 to 51,270,415, reverse strand). Ensembl gene ENSG00000170545.
Subcellular location: Cell membrane; Cytoplasmic vesicle membrane
Subcellular location (Human Protein Atlas): Plasma membrane; Cell Junctions; Nucleoplasm
Gene Ontology:
Molecular function: protein binding
Cellular component: cell junction; cytoplasmic vesicle membrane; plasma membrane
Genetic constraint (gnomAD): Loss-of-function variants: 7 observed, 9.02 expected, observed/expected ratio (o/e) 0.78, 90% interval 0.44 to 1.45. That is too few expected variants to judge how well the gene tolerates losing a copy. Missense variants: 113 observed, 109.59 expected, observed/expected ratio (o/e) 1.03, 90% interval 0.88 to 1.21. Synonymous variants: 49 observed, 45.42 expected, observed/expected ratio (o/e) 1.08, 90% interval 0.86 to 1.37.
Homologues: Orthologues: chimpanzee SMAGP (99% identical), macaque SMAGP (97% identical), dog SMAGP (86% identical), guinea pig SMAGP (84% identical), pig SMAGP (80% identical), mouse Smagp (78% identical), rat Smagp (75% identical), rabbit SMAGP (73% identical), Drosophila melanogaster Fas3 (13% identical), zebrafish si:ch211-214p13.3 (9% identical), zebrafish si:ch211-222f23.6 (9% identical), zebrafish zgc:113337 (9% identical), and 3 more. Paralogues in human: CADM1 (24% identical), NECTIN2 (20% identical), CADM2 (19% identical), CADM4 (19% identical), NECTIN1 (18% identical), CADM3 (16% identical), NCR3 (16% identical), NECTIN4 (15% identical), CRTAM (14% identical), NECTIN3 (14% identical), PVR (13% identical), TIGIT (9% identical), and 2 more.
Diseases named in the same sentence as SMAGP in open-access papers:
SMAGP is named in the same sentence as 2 diseases in open-access papers, as found by Europe PMC text mining. Sharing a sentence is not in itself a finding about the gene and the disease. The quoted sentences say what the papers report.
glioblastoma (1 paper, 2024). The most malignant astrocytic tumor (WHO grade IV). "SMAGP knock-down can inactivate the PI3K/Akt pathway, thereby inhibiting the malignant phenotypes of glioblastoma cells." (PMID 38478326, 2024).
tumor (1 paper, 2022). "SMAGP encodes a transmembrane glycoprotein that plays an important role in tumor invasion and metastasis." (PMID 35273597, 2022).